AGO1 (argonaute RISC component 1)
Diseases named in the same sentence as AGO1 in open-access papers (continued):
Sharing a sentence is not in itself a finding about the gene and the disease.
infection (70 papers, 2011 to 2026). The state of being infected such as from the introduction of a foreign agent such as serum, vaccine, antigenic substance or organism. "Using a polyclonal antibody specific to SlyAGO4a, our results suggest that Fol‐milR1 associates with SlyAGO4a to reduce plant immunity, leading to effective infection, which is an AGO1‐associated independent invasion strategy." (PMID 33960431, 2021). "In contrast, Arabidopsis ago1 mutants were more susceptible to infection with S. sclerotiorum, while ago1 overexpression led to increased resistance." (PMID 33921761, 2021). "Over one hundred HpasRNAs were detected to associate with the plant AGO1/RISC during infection, with 34 HpasRNAs being predicted to silence 49 plant targets including stress-related genes." (PMID 32441255, 2020). "When HCPro’s capacity to interact with AGO1 was compromised by the W208A mutation, consequences for the infection were detrimental." (PMID 33031436, 2020). "Interestingly, the expression of miR168a-5p or miR168b-5p that target the key component of the gene silencing pathway, AGO1, was significantly (P < 0.05) increased in the susceptible genotype but decreased in the resistant genotype after infection." (PMID 32531477, 2020). "Additionally, hypomorphic ago1 mutants, deficient in the sense transgene, mediate silencing and are hypersusceptible to infection by cucumber mosaic virus (CMV), indicating that AGO1 plays crucial roles in sensing transgene-mediated silencing and virus defense." (PMID 38005916, 2023). "As part of its pathogenicity, B. cinerea releases extracellular small RNAs (Bc-sRNAs) that enter plant cells during infection and recruit the plant`s own AGO1/RISC to induce host gene silencing for promoting infection." (PMID 38117848, 2023). "The expression level of Ago1 was selectively and strongly upregulated, while the Ago2 level remained unaltered in infected cells, both at 24 and 48 h post-infection." (PMID 38098491, 2023). "For example, increased expressions of Ago1 and Dicer1 were detected upon slow bee paralysis virus (SBPV) infection in bumblebees and linked to 17 differentially expressed miRNAs upon infection." (PMID 38098491, 2023). "Here we show that infection with the Turnip yellow mosaic virus (TYMV) is enhanced in Arabidopsis ago1, ago2 and dcl4 mutants, which are impaired in the execution of PTGS, but not in dcl2, rdr1 and rdr6 mutants, which are impaired in the amplification of PTGS." (PMID 36696453, 2023). "Upon TYLCV infection, the expression of both sly-miRNA168 and its target AGO1, were induced, while the AGO1-derived phasiRNAs were reduced." (PMID 38110861, 2023). "How many of the remaining Leishmania-modulated Ago1-dependent host proteins have a role to play in Leishmania-infection related activities remains to be investigated." (PMID 38098491, 2023). "Taken together, our data demonstrate that V. dahliae produces abundant 24-nt VdrsR-1 VdsRNAs that are secreted into plant host cells during infection and that VdrsR-1 is a bona fide trans-kingdom VdsRNA loaded into the host AGO1 protein." (PMID 35519822, 2022). "After infection, cucumber mosaic virus and tomato aspermy virus produce viral proteins that interact with the AGO1 protein to disrupt the cleavage of the AGO1." (PMID 36714724, 2022). "In this study, Bc-siR3.2 hijacked the host RNAi machinery by loading into AGO1 to target plant mitogen-activated protein kinase transcripts, thereby suppressing host immunity to facilitate infection." (PMID 35519822, 2022). "The up-regulation of 22-nt Pgt sRNAs with enrichment for 5′ adenines during late infection coincides with the up-regulation of the AGO1 gene." (PMID 34526021, 2021). "Bc‐siRNAs were shown to associate with plant Argonaute 1 (AGO1) protein to suppress host immunity, as well as to target host plant mitogen‐activated protein kinase transcripts during infection." (PMID 33960431, 2021).
infection (continued). "We mined previously published expression data to assess if the RNAi genes are expressed during host infection and if Ago1 is upregulated." (PMID 34208898, 2021). "In total, 66 fungal sRNA were upregulated during in planta infection of Z. tritici, all of which would represent interesting targets to further dissect the mechanisms of dicer-independent effects of Ago1 on the infection of Z. tritici in planta." (PMID 34208898, 2021). "It is possible that this results in a shift in the AGO1/AGO2 balance leading to the unmasking of AGO2-dependent defense during PVA infection." (PMID 33031436, 2020). "During an infection, when AGO1 is targeted by viral silencing suppressors, AGO2 expression is upregulated." (PMID 33031436, 2020). "The highest infection reduction of 60% was reached with dsRNAs targeting ago1/ago2_365nt and ago1/dcl1_1570nt." (PMID 32411160, 2020). "It was clear that while AGO1 targeted the HCPro-less virus in a defensive manner it has a positive effect on the infection in the presence of a functional HCPro." (PMID 33031436, 2020). "Based on these findings we suggest that potyviral HCPro recruits host AGO1 through its WG motif and engages AGO1 in the production of stable virus particles, which are required for an efficient systemic infection." (PMID 33031436, 2020). "Previous studies with the CymRSV system revealed that at infection times of >4 days postinoculation (dpi), AGO1 expression is induced in the infected plants, which correlates closely with the accumulation of viral RNA." (PMID 29691336, 2018). "AGO2 and AGO5 restrict infection in leaves, while AGO1 and AGO10 protect inflorescence from systemic infection by TuMV." (PMID 29538326, 2018). "For example, soybean mosaic virus (SMV) strain G7 infection induced the overexpressed AGO1 mRNA to trigger the AGO1 siRNA-mediated AGO1 mRNA degradation pathway, resulting in the reduced AGO1 level, which requires SGS3, RDR6 andSDE5 as well as DCL4/2." (PMID 28869553, 2017). "Silencing of Ago1 resulted in a decrease of replication of the tested mosquito-borne viruses, suggesting an importance of the miRNA pathway for a successful infection in Aag2 cells for these viruses." (PMID 28060823, 2017). "In contrast, during Cym19stop-infection AGO1-loading occurred as expected predominantly by 5’U-sorting of vsiRNA and endogenous sRNAs." (PMID 27711201, 2016). "Intriguingly, we found that AGO18, a member of a new AGO clade that is conserved in monocots, is specifically induced by the infection of two taxonomically different viruses and is required for the antiviral function of AGO1." (PMID 25688565, 2015). "This lends indirect support from our notion that 2b can substitute HCpro with high efficiency in viral translation and infection, as 2b was demonstrated to suppress AGO1 in PBs." (PMID 26641460, 2015). "The authors expressed their concern in interpreting infection results for AGO1 due to the large number of genes that are deregulated when AGO1 is disrupted, including AGO2 induction." (PMID 26641460, 2015). "Surprisingly, systemic infection of inflorescence tissue was detected in the ago1–27 ago10–5 double mutant and ago1–27 ago2–1 ago10–5 triple mutant plants." (PMID 25806948, 2015). "Local infection of single ago1 mutants was significantly lower than that of wild-type Col-0, but this was likely due to the difficulty of inoculating the smaller leaves of hypomorphic mutants containing ago1 alleles." (PMID 25806948, 2015). "In such a scenario, the P0 proteins from poleroviruses would destroy AGO1 at an early step to prevent viral siRNAs produced during infection to be incorporated into novel RISCs and this would compromise antiviral RNA silencing." (PMID 24795741, 2014). "For example, the fluctuation of miR168 can influence the fluctuation of AGO1 which is the main component in RNA-induced silencing complex that functions to prevent infection." (PMID 24386476, 2013).
infection (continued). "In addition, it was of interest to analyze the Leishmania-modulated Ago1-dependent proteins in relation to other intracellular pathogen infections." (PMID 38098491, 2023). "The transcripts of dcl2 and ago1 of F. graminearum accumulate at lower levels after infection by Fusarium graminearum virus 1 (FgV1) than by FgV2 or FgV3, and AGO1 also involves the accumulation of virus-derived siRNAs (vsiRNAs) in FgV1-infected F. graminearum strain." (PMID 38033556, 2023). "Among the proteins downregulated by infection and recovered by Ago1-knockdown, Cathepsin L (CTSL) has been shown to play a crucial role for a Th1-type immune response during L. major infection by processing of soluble Leishmania antigen (SLA) for presentation on MHC class II molecules." (PMID 38098491, 2023). "Similarly, the Ago-1-overexpressed F. graminearum mutant showed a significantly higher mycelial growth after FgV1 inoculation, compared to the wild type after FgV1 infection." (PMID 35893542, 2022). "Thus, the present study presumes that, in addition to the CMV CP regulation of 2b and CMV 1a‐mediated regulation of the 2b–AGO1 association, the equilibrium between CMV‐2b and CsRDR1c protein levels controls virus accumulation and the infection progress." (PMID 34355485, 2021). "Surprisingly, they did not observe any qualitative phenotypic difference of Dcl, Ago1 and Ago2 mutants during infection of the susceptible wheat cultivar Bobwhite." (PMID 34208898, 2021). "Most importantly, we identify an effect of the Ago1 gene specific for infection in planta." (PMID 34208898, 2021). "However, deletion of Ago1 significantly reduced the ability of Z. tritici to produce asexual fructifications (pycnidia) during infections of the wheat cultivar Obelisk." (PMID 34208898, 2021). "Interestingly, the Ago1 gene also showed the highest expression of all four Z. tritici Argonaute genes during plant infection, further supporting relevance during host infection." (PMID 34208898, 2021). "Likewise potato virus X (family Alphaflexiviridae) p25 and enamovirus (family Luteoviridae) P0 have been suggested to alleviate defensive pressure on the infection by directing AGO1 to degradation." (PMID 33031436, 2020). "In addition, we demonstrate that the viral HCPro and, more specifically, a conserved WG motif therein, is responsible for engaging AGO1 in the promotion of the infection." (PMID 33031436, 2020). "This proposes that the functions of AGO1-HCPro binding in infection in the close relatives of potyviruses, the ipomoviruses, may have been substituted with some alternative mechanisms." (PMID 33031436, 2020). "As our results hinted AGO1 could benefit the infection instead of countering it, we were interested in exploring the mechanisms and viral factors involved." (PMID 33031436, 2020). "Furthermore, we report the relevance of the interaction for the systemic spread of the infection and suggest that AGO1 contributes to the success of potyvirus infection by enabling the accumulation of stable virions." (PMID 33031436, 2020). "However, the possibility remains that the ubiquitination process plays important roles in the AGO1 degradation triggered by P0 or infection of poleroviruses." (PMID 30664234, 2019). "Thus, in close agreement with earlier reports, we measured an augmented level of AGO1 mRNA in the infections with the wt CymRSV at 4 dpi." (PMID 29691336, 2018). "In contrast, the AGO1 mRNA levels were closely comparable in the two types of infections." (PMID 29691336, 2018). "Infections with the p19-expressing wild-type (wt) CymRSV were further shown to induce the expression of miR168, which, in turn, inhibits additional accumulation of AGO1 protein at 5 dpi or later." (PMID 29691336, 2018). "Infection of rdr1-1, rdr6-15, and ago2-1 single-mutant plants by suppressor-deficient TuMV-AS9-GFP is restricted to cauline leaves, while inflorescence remains uninfected due to the redundant antiviral activity of RDR1 and RDR6, and AGO1 and AGO10." (PMID 29538326, 2018).
infection (continued). "In addition, Dicer1, Dicer2, Drosha, and Ago1 are involved in miRNA biogenesis and increased polysome loading after infection in mosquitoes." (PMID 29718912, 2018). "Our results showed the increased expressions of dicer-1 and ago-1 upon SBPV infection." (PMID 28374846, 2017). "Together, these pieces of evidence strongly support that miR168/AGO1 modulation might play an important role in shaping host responses to pathogen infection, including infection by fungal pathogens." (PMID 25491154, 2014). "Presumably, an elicitor-regulated adjustment of miR168 levels might contribute to the maintenance of the appropriate levels of AGO1, and accordingly of miRNA functioning, during the plant defense response to pathogen infection." (PMID 25491154, 2014). "During infection, P38 inactivates AGO1 by down-regulating miR162." (PMID 21864377, 2011). "However, E/V infection robustly potentiated the transcription of the RNAi pathway components, including Dcr-2 in the siRNA pathway, AGO3 in the piRNA pathway, and Drosha, Dcr-1, and AGO1 in the miRNA pathway, while E/C infection exerted little effect on the RNAi pathways." (PMID 36511715, 2023). "However, FgV1 overcomes this RNA silencing machinery and further suppresses the RNAi pathways of the host themselves via the suppression of Dicer-2, Ago-1, and dcl2 in F. graminearum to establish its infection in the host by interfering with the host’s antiviral response." (PMID 35893542, 2022). "Previous studies also reported that changes in the expression of miR168 and AGO1 mRNA are not always negatively correlated, Nevertheless, the decrease in the expression of AGO1 protein could alleviate the host RNA-silencing-mediated defense to benefit for the infection of the virus." (PMID 32178444, 2020). "ASRs depending on Ago1 might suppress apoptosis, terminal phase of lytic infection." (PMID 24627180, 2014). "Compared to mock-inoculated controls, TMV-GFP infection in V. dahliae induced the up-regulation of the DCL1 and AGO1 transcripts of only 1.5-fold at the first sampling time, which is consistent with a 1.2-fold increase in viral load." (PMID 41003165, 2025). "Infection by soybean mosaic virus (SMV) strain ‘G7’ led to the accumulation of miR168 and the AGO1 (ARGONAUTE1) mRNA." (PMID 40585574, 2025). "Once inside, they hijack the plant’s Argonaute 1 (AGO1) protein to silence defense-related genes, facilitating infection." (PMID 40985376, 2025). "In this study, we constructed RNAi component mutants for each of DCL1, DCL2, AGO1, AGO2, RDRP1, RDRP2, and RDRP3, and analyzed sRNA profiles in A. flavus to explore the role of each RNAi component in AfPV1 infection of A. flavus." (PMID 38033556, 2023). "At this stage of the infection, the contribution of the auxiliary AGO genes such as AGO1, AGO5, and AGO10 to the antiviral response would also become substantial." (PMID 37603044, 2023). "In the comparison of VEEV and E/V, despite the enhanced transcriptions of AGO3, Drosha, Dcr-1, and AGO1, the corresponding fold change values after VEEV infection were significantly lower than those induced by E/V infection." (PMID 36511715, 2023). "The expression levels of DCL2, AGO1, RDRP3, RDRP4, and RDRP5 were significantly increased by FgV2 and FgV3 infection." (PMID 38033556, 2023). "In contrast, TuGK infection induces ARF16 accumulation to approximately 1.5-fold levels, whereas the RNA levels for AGO1 and MYB33 were similar to those obtained with the mock plants." (PMID 36650505, 2023). "For example, AGO1 and SGS3 are degraded via autophagy during Polerovirus, TuMV, or TYLCCNV infection." (PMID 34587220, 2021). "RISCs that include AGO1, 2, 3, 4, 5, and 9 can bind to virus sRNA and Arabidopsis AGO5 can bind potato virus X (PVX) sRNA in N. tabacum and suppress the infection thereof, but only in the presence of an intact AGO2 interaction." (PMID 32528501, 2020). "AGO1 strongly enhanced potato virus A (PVA) particle production and benefited the infection when supplied in excess." (PMID 33031436, 2020).
infection (continued). "We found no obvious differences in the total accumulation levels of Dicer, AGO1, AGO2, PACT, or TRBP in 293T cells after infection with IAV-PR8, IAV-WSN, or Sendai virus." (PMID 33281788, 2020). "Infection with TRV empty vector or silencing constructs resulted in changes in expression of RDRs (RDR1, 2, 6), DCLs (DCL1–4) and AGOs (AGO1, 2, 4)." (PMID 27099376, 2016). "During infection, CMV 2b directly interacted with AGO1 and specifically inhibited its slicing activity." (PMID 26225990, 2015). "To confirm whether Ago1 participates in regulating HIV proviral expression, we utilized the dual-labeled HIVGKO reporter virus, which more closely mimics natural infection by allowing the study of HIV expression across multiple integration sites." (PMID 40840622, 2025). "Similarly, the preferential accumulation of 21-nt 5′ uracil sRNAs in germinated spores and during early infection correlates with high-level expression of AGO2 and relatively low expression of AGO1." (PMID 34526021, 2021). "Conversely, early in infection, p19 binds miR403 and the expression of the antiviral AGO2 is increased, whereas the low affinity of p19 for AGO1-regulating miR168 ensures homeostasis of AGO1." (PMID 34565394, 2021). "First, the HC-Pro suppressor encoded by TuMV has no inhibitory effects on AGO1-dependent miR403-guided cleavage of AGO2 transcripts, confirming the absence of VSR activity in cells undergoing early stages of infection at the virus front." (PMID 33230160, 2020). "Infection of these cells with NDV also triggered an aggregation of mRFP-DCP1a (≥ 60% of cells), which colocalized with NDV NP, but not AGO1, suggesting that AGO1 and its associated RISC pathway were unlikely involved in this event." (PMID 32034313, 2020). "Noneffective sequestration of miR168; the AGO1 level remains unaffected at the early infection stage." (PMID 29691336, 2018). "Local TuMV-AS9-GFP infection foci were observed in inoculated rosette leaves, and virus was detected in noninoculated cauline leaves, from ago1–27 ago2–1 double mutant plants, but ago1–27 had no enhancing or suppressing effects when combined with ago2–1." (PMID 25806948, 2015). "However, infection of ago1-25 plants with Fny-CMV intensified aphid resistance, suggesting that the virus can induce additional, AGO1-independent aphid resistance mechanism(s)." (PMID 24349433, 2013). "Notably, no obvious changes in the subcellular accumulation of AGO1, AGO2, and PACT were observed in 293T cells after infection with the mutant of IAV-WSN deficient in the expression of NS1 (WSNΔNS1, lane 3)." (PMID 33281788, 2020). "From this point of view the pro-viral effect of AGO1 would be indirect because the higher AGO2 levels could explain the negative impact the silencing of AGO1 had on the infection." (PMID 33031436, 2020). "Given the established role of AGO1 in antiviral defense in Arabidopsis, we tested whether AGO1 functions similarly in rice by inoculating an ago1 RNAi line by viruliferous brown planthopper carrying RSV to recapitulate the natural infection conditions." (PMID 25688565, 2015). "Thus, both the lack of TuMV-AS9-GFP infection in single ago1 mutants and the lack of systemic infection of inflorescence in ago1–27 ago2–1 double mutants were not due to pleiotropic effects." (PMID 25806948, 2015). "Upregulation of Ago1 during intracellular infection is not unique to Leishmania infection, and changes in host RISC composition have also been reported in other infections." (PMID 38098491, 2023). "Non-grafted UCTC plants responded to infection of CMV-77 by up-regulation of DCL2, AGO1, AGO2, and RDR1 transcripts whereas only AGO1 was up-regulated in Ma." (PMID 32824316, 2020). "However, we detected a markedly enhanced accumulation of AGO1, AGO2, and PACT, but not Dicer or TRBP in the nucleus of 293T cells after infection with IAV-WSN compared to mock infection or infection with IAV-PR8 or Sendai virus (lane 2)." (PMID 33281788, 2020).